IL6 (interleukin 6)
Diseases named in the same sentence as IL6 in open-access papers (continued):
Sharing a sentence is not in itself a finding about the gene and the disease.
cancer (continued). "Analysis using the ‘Cancer Hallmark’ gene set indicated that the top pathways suppressed by JGT in SI rats were IFNα and IFNγ, and inflammatory responses and IL6/JAK/STAT3 signaling, that is, the same pathways that were activated in SI rats compared with GH rats." (PMID 36980301, 2023). "Interestingly, the microbiota of mice with aberrant inflammasome signaling promotes cancer through local secretion of IL-6, which in turn promotes proliferation of epithelial cells and creates a precancerous state." (PMID 37555952, 2023). "Extensive research has been conducted on the role of cancer-associated fibroblasts (CAFs) in solid tumors, particularly in relation to their production of soluble factors such as IL-1α, IL-1β, CXCL1, CXCL12, G-CSF, and IL-6." (PMID 37880682, 2023). "Sofia’s team identified key pathways that could potentially slow down cancer cell growth, emphasizing the roles of dendritic cells and the secretion rate of IL-6 as promising targets for inhibiting or decelerating cancer growth." (PMID 38002445, 2023). "The IL-6/STAT3/VEGFA signaling pathway is activated in different cancers." (PMID 36720310, 2023). "Furthermore, H. pylori infection is also known to stimulate the production of proinflammatory cytokines such as IL-1β, TNF-α, and IL-6, thus creating a microenvironment that promotes cancer cell growth and survival." (PMID 37325512, 2023). "These cells secrete IL-6, IL-23, IL-22, IL-17, IL-1β, and TGF-β, causing cancer cell proliferation." (PMID 37762693, 2023). "As part of the STAT3 pathway, IL-6 is a multifunctional cytokine produced by many cell types and is conducive to normal development of tissue regeneration, immune response, autoimmunity, and a multitude of cancers." (PMID 38002302, 2023). "We have confirmed that alterations in the composition of oral bacteria can contribute to a reduction in SCFAs and the expression of the FFAR 2, resulting in an inflammatory response through the upregulation of TNFAIP8 and the IL-6/STAT3 pathway, ultimately increasing the risk of cancer onset." (PMID 37296861, 2023). "Moreover, we identified MDSC secreted IL-6/IL-10/IL-1β induced STAT1/STAT3/NF-κβ signaling axis as a targeted cascade to promote early drug resistance in cancer cells." (PMID 38304256, 2023). "IL-6 may promote cancer cell migration and invasion by enhancing the PLOD2-integrin β1 signaling pathway in OSCC cells." (PMID 36614179, 2023). "The upregulation of plasma levels of VEGF-A, TNF-α, CCL2, IL-6, and IFN-γ in Cancer TIF1-γ-DM patients could provide insight into the underlying mechanism of the pathogenesis of Cancer TIF1-γ-DM." (PMID 36357631, 2023). "Interestingly, in this study, the authors showed that the concentrations of Pentraxin 3 were significantly correlated with the concentrations of NF-kB and IL-6, which confirmed the involvement of PTX3 in cancer-associated inflammation." (PMID 38136377, 2023). "IL-6 serum concentration, which is usually in the picogram per milliliter range in humans, can rapidly increase up to 1000-fold under certain pathological conditions, including inflammatory diseases and cancer." (PMID 37187893, 2023). "Other cancer cell‐derived cachexokines, inflammatory cytokines, and metabolic messengers, such as ataxin‐10, IL‐6, and D2‐HG, are also involved in metabolic alterations, dysfunctional glucose uptake, promotion of tumor growth, and increased cardiac muscle wasting." (PMID 37654192, 2023). "IL-6 signaling plays a complex role in inflammation and cancer." (PMID 36875137, 2023). "Further studies will be interesting to define whether SC-1 alleviates the oncogenic transformation of cancer by blocking TGFβ-induced IL-6 expression." (PMID 37511415, 2023). "Indeed, cytokines such as IL-6, TNF-α, and TGF-β have been closely related to cancer-associated muscle wasting, since they disrupt muscle proteostasis, as well as mitochondrial biogenesis and function." (PMID 38136400, 2023).
cancer (continued). "STAT3 can be activated in cancer cells in a constitutive or IL-6-induced manner." (PMID 37103357, 2023). "Furthermore, significant positive correlations were observed among VEGF-A and three cytokines, such as CCL2, IL-6, and IFN-γ, and a positive association between IL-6 and IFN-γ within the Cancer TIF1-γ-DM group." (PMID 36357631, 2023). "Interleukin 6 (IL-6), a cytokine that is produced during acute and chronic inflammation, triggers several signalling cascades in cancer that affect cell proliferation and survival, the inhibition of apoptosis, and the induction of anti-cancer drug resistance." (PMID 37047727, 2023). "However, evidence has demonstrated that IL-6 plays a critical role in cancer progression and resistance to therapeutics." (PMID 36794014, 2023). "Recombinant IL-6 has been shown to help mobilize a T-cell response against cancer." (PMID 37461742, 2023). "In addition, higher expression of IL-6 was shown in cancerous tissues than in adjacent non-cancer tissues in early-stage CC patients, confirming its association to cancer development." (PMID 38064478, 2023). "It has been described that under specific circumstances, IL-6 and IL-10 could favor cancer development." (PMID 37122717, 2023). "Indeed, whereas most studies have identified STAT3 as positive regulator of cancer progression, other investigations pointed out that the IL-6/STAT3 axis can be a protective element in cancer." (PMID 37190183, 2023). "Interleukin (IL)-1β and IL-6 are proinflammatory cytokines involved in cancer progression." (PMID 37068081, 2023). "In RA patients, prolonged and sustained activation of the immune system may drive the initiation and progression of cancer, potentially mediated by interleukin-6 (IL-6), which could serve as a common link between RA and cancer." (PMID 37957703, 2023). "Thus, IL‐6 has become a useful biomarker in the evaluation of cancer prognosis and effectiveness of anti‐cancer treatment." (PMID 36419386, 2023). "Neutralization of IL-6 partially suppresses PDAC cell growth, suggesting that there might be other factors besides IL-6 driving the cancer-promoting molecular signals originating from the adipocytes." (PMID 36074246, 2023). "Interestingly, we also observed that the expression of CDH2, SPP1, TNC, CYR61, SERPINA1, and IL6 correlated with the progression of individual cancer stages." (PMID 37887075, 2023). "One study has found that IL-6, as a proinflammatory factor, can promote cancer metastasis." (PMID 36844875, 2023). "In addition, we also noted that SRSFs expression was correlated with the activation or inhibition of multiple immune-related pathways in different cancer types, such as interferon alpha response, interferon gamma response, Il-6/JAK/STST3 signaling and so on." (PMID 38015716, 2023). "Additionally, the activation of TLR4 by Hsp70/90 Evs has also been found to be responsible for the systemic rise in the levels of inflammatory cytokines, including TNF-α and IL-6, during cancer cachexia." (PMID 37998333, 2023). "Our findings suggest that targeting IL-6 and its regulatory pathway may enhance the responsiveness of cancer cells to svLAAOs-based anticancer therapies." (PMID 37385076, 2023). "Although IL-6 may be produced by macrophages and cancer cells in vivo, our results demonstrate that these inhibitors have the potential to reduce inflammatory mediators driving metastasis." (PMID 37397366, 2023). "In cancer cells, IL-6 increases the expression of downstream STAT3 targets." (PMID 37753372, 2023). "Furthermore, elevated neutrophils can produce more inflammatory transmitters, such as interleukin (IL)-1, IL-6, IL-17, vascular endothelial growth factor, and other immunomodulatory transmitters, leading to angiogenesis and the progression of malignant tumors." (PMID 37621681, 2023).
cancer (continued). "The typical proapoptotic function of pro-inflammatory cytokines (IL-1β, TNF-α, and IL-6) can actually increase cancer cell survival via mitogen-activated protein kinase/extracellular signal-regulated kinases (MAPK/ERK) or phosphoinositide 3-kinase/ protein kinase B (PI3K/Akt)-dependent pathways." (PMID 37555952, 2023). "In fact, noncoding RNAs, in particular post-transcriptional microRNA regulatory loops linked to IL-6, may contribute to EMT plasticity and support cancer cell invasion." (PMID 36814597, 2023). "In a pathological context, IL-6 plays a significant role in cancer development." (PMID 37892997, 2023). "Interestingly, other markers like ghrelin and myostatin remained stable, further implicating IL‐6 and NF‐κB signaling as key mediators of cancer cachexia." (PMID 37533407, 2023). "IL-6 in particular is a key enhancer of survival and metastasis in cancer." (PMID 37534795, 2023). "A strong increase was observed in the serum levels of proinflammatory cytokines in rats treated with DEN, and these results were associated with cancer and inflammation (especially TNF-α and IL-6), which have been documented to be increased after the administration of DEN27." (PMID 36949140, 2023). "Chronic inflammation is a main backer to the occurrence of cancers and pro-inflammatory cytokine IL6 could boost glycolysis in cancer cells via serum sEV-derived miR-155." (PMID 37208722, 2023). "Serum IL6 can be released by macrophages, monocytes, fibroblasts and cancer cells." (PMID 37062842, 2023). "IL-6 controls cancer stem cell renewal and induces cancer cell migration, and EMT." (PMID 36835413, 2023). "IL-6 activation of STAT3 was found to downregulate miR-34a in cancer cells." (PMID 35740998, 2022). "have reported that IL-6 and granulocyte-macrophage colony-stimulating factor (GM-CSF) released from cancer cell-activated CAFs through co-culture of monocytes and CAFs can increase TAM infiltration and metastasis and direct monocytes to differentiate into M2 TAMs." (PMID 35464435, 2022). "Moreover, IL-6 drives many cancer hallmarks through the downstream activation of the STAT3 signaling pathway." (PMID 36547079, 2022). "While miR-181a-3p and both miR-195a-5p and miR-125b-1-3p induced muscle atrophy by activating apoptotic signaling pathways, a decrease in miR-497-5p mediated by IL-6, counteracted muscle atrophy by stimulating expression of hypertrophy-related genes in cancer cachexia." (PMID 35994202, 2022). "Inflammatory agents, including IL-1β, IL-6, and IFN-γ, play a key role in DNA methylation, and thereby have a close association with cancer, and the JAK-STAT cascade is a bridge between inflammation and cancer." (PMID 35184640, 2022). "The IL-6 associated JAK/STAT signaling pathway plays an important role in cancer development, and has proven to exhibit multifaceted properties to be considered as a therapeutic target for the treatment of cancer." (PMID 35295334, 2022). "ApcMin/+ mice, mice that bear a germline mutation in the adenomatous polyposis coli gene (APC), have elevated serum levels of IL-6, and they develop muscle tissue loss and the cancer cachexia phenotype, whereas, ApcMin/+/IL-6−/− mice do not." (PMID 35743911, 2022). "To conclude, assessing the circulating levels of IL‐6 could be a useful method of monitoring the development of cancer cachexia and future trials should aim to integrate the cytokine in the multifactorial management of this disorder." (PMID 35080147, 2022). "However, LA intervention reduces the redox threshold of cancer cells closer to the normal cells and triggers an inflammatory response through IL6 signaling." (PMID 35360165, 2022). "The authors suggested that blockade of the IL-6 signaling pathways might reduce production and secretion of IL-6 leading to an increase in the potential effect of the agent involving inhibition of IL-6 or IL-6R in cancer." (PMID 36091805, 2022).
cancer (continued). "IL-6, IL-8, or TNF-α production by DCs stimulated by commensal bacteria, demonstrated in this study, may be associated with IBD and cancer." (PMID 35739324, 2022). "IL-6 inhibition combined with other chemotherapeutic drugs, radiation, and targeted therapies significantly increased the clinical therapeutic gain in various cancer types." (PMID 36405719, 2022). "To confirm whether FGFC1 exerts anti-cancer effects via the NF-κB signaling pathway in vivo, we analyzed the expression of p-p65, IL6, and TNF-α in PC9 xenograft tumors." (PMID 35049931, 2022). "Importantly, the growth-enhancing effects of IL-6 on cancer cells also extend to cancer stem cells, capable of self-renewal and expansion, which require STAT3 to act synergistically with stem cell transcription factors such as NANOG." (PMID 36313280, 2022). "Our data indicating activated STAT3 may support the induction of Il-6 mRNA via contributing to stabilisation of NF-κB in the nucleus, leading to chronic activation of NF-κB as shown in cancer models." (PMID 36275769, 2022). "In addition, functional assays were conducted to determine the effect of APE1 shRNA on malignant phenotypes of cancer cells in vitro and in vivo and the activation of IL‐6/STAT3 signalling." (PMID 35605028, 2022). "Given this strong relationship between inflammation and cancers, chronic inflammatory markers are sometimes used as a predictor and assessment tool to determine cancer status, such as interleukin (IL)-6 and tumor necrosis factor-a (TNF-α), in hepatocellular carcinoma recurrence." (PMID 35892729, 2022). "The expression of IL6 in the blood and tissues of patients with cancer is significantly increased." (PMID 35590327, 2022). "A recent meta-analysis summarized 54 studies and suggested that peripheral blood inflammatory markers (CRP, TNF and IL-6) were significantly related to cancer-related DepS and might be helpful for management of DepS in the cancer patients." (PMID 36615742, 2022). "Interleukin (IL)-6 is a pro-inflammatory cytokine that has been identified as a key mediator in promotion of PCa growth, PCa progression to the castration-resistant state, promotion of cancer metastasis and resistance to chemotherapy." (PMID 35194188, 2022). "A large body of evidence supports the connection between IL-6 and cancer development." (PMID 35326661, 2022). "In addition, autocrine synthesis of IL-6 has been observed in a wide range of malignant tumours, including OSCC." (PMID 35484352, 2022). "In addition, the results of Pearson correlation analysis identified a positive correlation of the expression of APE1 in cancer tissues of NSCLC patients with that of IL‐6 in serum." (PMID 35605028, 2022). "Notably, FIB was found to act not only as an inhibitor of lymphocyte adherence and cytotoxicity against cancer cells but also as a source of induction of IL-6." (PMID 36153540, 2022). "In conclusion, the evidence demonstrates that IL-6 is a critical participant in the inflammatory process of cancers, the microbiota may also play a role in the pathway in conjunction with IL-6." (PMID 36140470, 2022). "High serum levels of IL-6 have also been observed in these cancer conditions." (PMID 35335997, 2022). "IL-6 promotes the invasion of cancer cells through the epithelial–mesenchymal transition." (PMID 36275775, 2022). "Therefore, the regulation of IL-6 plays a key role in suppressing chronic inflammation in menopausal women, which ultimately reduces the incidence of cancer and slows down its progression." (PMID 35707470, 2022).
cancer (continued). "The tested conjugates decreased IL-6 release in both cancer cell lines by almost 50%." (PMID 35053570, 2022). "IL6/JAK/STAT3 signaling was reported to facilitate cancer progression in multiple cancer." (PMID 36276992, 2022). "IL-6 is a pleiotropic cytokine that induces cancer chemotherapy resistance in various ways." (PMID 36679900, 2022). "Many cytokines can exhibit either pro- or anti-cancer properties, including interleukin-6 (IL-6)." (PMID 35371975, 2022). "A similar action is known for IL6, which plays a key role in cancer progression." (PMID 35887223, 2022). "Interestingly, as described for trophoblast invasion, IL-6 is also expressed and secreted by cancer cells and cells in the TME." (PMID 35625802, 2022). "Accumulated evidences have shown the role of IL-6 in progression of different types of cancers." (PMID 35300689, 2022). "Cytokines such as interleukin-6 (IL-6) may have a significant impact on cancer progression through signal cascades." (PMID 36591515, 2022). "In the late stages of cancer, IL-6/STAT3 may promote the gain of invasive activity and the metastatic dissemination of cancer cells by inducing epithelial–mesenchymal transition (EMT) transcription factors (EMT-TFs), such as SNAI1 and TWIST." (PMID 36010693, 2022). "In RDEB patients, IL-6 may indeed promote cancer progression through both fibrosis and CAF activation, thus providing an interesting link between systemic inflammation and cancer development." (PMID 35456044, 2022). "Cancer-associated fibroblasts (CAFs) can inhibit both the innate and adaptive antitumor immune response by secreting numerous chemokines and cytokines, such as TGF-β, IL-6, IL-8, IL-13, CXCL12, CXCL14, and VEGFA." (PMID 35646893, 2022). "Furthermore, downregulation of GRP78 by ISL inhibited TGF-β1 secretion from the cancer cells and prevented the activation of CAFs and the inhibition of IL-6, TGF-β1, and MMP-9 by CAFs." (PMID 35740372, 2022). "Moreover, a wide range of studies have identified the physiological and pathological roles of IL-6 in inflammation, immune and cancer." (PMID 35924148, 2022). "TAMs are known to secret protumor soluble factors, including IL-6, in several cancers." (PMID 35835809, 2022). "It was also shown that without IL-6, cancer progression slows even in the presence of the Kras mutation." (PMID 35800364, 2022). "Indeed, it is likely to be an over-simplification to expect that an isolated reduction to IL-6 corresponds with a direct reduction to cancer growth." (PMID 35359426, 2022). "Although M1-like TAMs show generally anti-tumoral effects, they may induce chronic inflammation, whereas the TIMP-1/IL-6 loop might foster STAT3 activation in cancer cells." (PMID 36291767, 2022). "Importantly, elevated IL-1β and IL-6 levels have been found in the serum of patients with pancreatic cancer, a cancer type that strictly relies on the inflammatory process." (PMID 35267528, 2022). "The blockade of IL‐6 signalling is already considered as an additional approach for anti‐cancer therapy, which may modulate CD8Low T cells as well based on our findings." (PMID 36504430, 2022). "IL-6/JAK2/STAT3 signaling pathway deserves attention in the treatment of human cancer." (PMID 36591515, 2022). "The coculture of CD4 Th cell lines from C5 with SW480 cell line showed a lower level of IL-17A because the SW480 cancer cells underwent apoptosis while high IL-6 was detected due to the high proliferation of CD4 Th cell lines from C5 which cause the cell cytotoxicity." (PMID 37529004, 2022). "M2 polarized macrophages secret IL-6 to enhance cancer cell migration." (PMID 36071472, 2022).